PRMT6 (protein arginine methyltransferase 6)
Diseases named in the same sentence as PRMT6 in open-access papers (continued):
Sharing a sentence is not in itself a finding about the gene and the disease.
breast carcinoma (continued). "Meanwhile, PER3 protein abundance was decreased, and was inversely correlated with the abundance of PRMT6 and PARP1, in breast cancer samples." (PMID 36941223, 2023). "In breast cancer MCF-7 cells, licochalcone A inhibits PRMT6-dependent methylation of histone H3 at arginine 2 (H3R2), resulting in a significant inhibition of estrogen receptor activity." (PMID 35311114, 2022). "It has been also reported that mouse embryonic fibroblasts from PRMT6−/− embryos undergo rapid cellular senescence and depletion of PRMT6 in MCF7 breast cancer cells induces senescence as well as cell cycle arrest." (PMID 29507670, 2018). "However, it was also reported that PRMT6 mRNA levels were lower in breast cancer compared to normal breast tissues, a discrepancy that could be due to the small number of samples analyzed in the latter study, as well as the different level of expression examined, mRNA versus protein." (PMID 27556302, 2016). "Several PRMT6-selective inhibitors, including MS117, SGC-6870, EPZ020411, and the natural compound licochalcone A, have demonstrated therapeutic potential in various solid tumors, including glioblastoma, lung, gastric, and breast cancers." (PMID 41204384, 2025). "Furthermore, the PRMT6 inhibitor RPZ020411 has demonstrated efficacy in halting IL-6/STAT3 signaling, which is essential for the proliferation of breast cancer cells." (PMID 40869229, 2025). "Moreover, knockdown of PRMT6 and PARP1 significantly impeded breast cancer cell invasiveness, whereas constraining PER3 expression restored it to normal levels." (PMID 36941223, 2023). "Then, we sought to determine whether simultaneous targeting of the enzymatic activity of PRMT6 and PARP1 elicits synergetic effects against breast cancer tumorigenicity." (PMID 36941223, 2023). "Furthermore, PARP1‐inhibition via Olaparib resulted in the dissolution of the PRMT6/PARP1/CRL4B complex, and strengthening the circadian rhythm amplitude and inhibiting breast cancer progression." (PMID 36941223, 2023). "The results showed that tumor growth was more strongly inhibited following combined administration of PRMT6 and PARP1 inhibitors, compared with either monotreatment, indicating a potent synergetic antitumor effect of the inhibitor in breast cancer." (PMID 36941223, 2023). "This suggests that lower PRMT6 expression may lead to increased expressions of PTEN and IGFBP3, decreased cell cycle progression and increased apoptosis of breast cancer cells." (PMID 35311114, 2022). "However, the extent to which PRMT6-mediated non-histone protein methylation influences cancer cell metastasis, particularly in the context of breast cancer, remains elusive." (PMID 37813837, 2023). "Meanwhile, ER status did not affect the role of PRMT6 in breast cancer." (PMID 36941223, 2023). "However, only a minority of the PRMT6-dependent transcriptional and splicing targets overlap, suggesting no generally simultaneous control of both processes by PRMT6 in NT2/D1 cells, in contrast to results received in breast cancer cells." (PMID 39900436, 2025). "PRMT6 gain‐of‐function cells exhibited augmented proliferation and colony numbers, while PRMT6 depletion decreased these effects in the triple‐negative cell line MDA‐MB‐231 and luminal breast cancer cell line MCF‐7 cells." (PMID 36941223, 2023). "At the same time, systematic studies using human breast cancer cell lines demonstrated that licochalcone A, a natural compound, is a novel, reversible and selective, non-S-adenosyl L-methionine (SAM) binding site competitive PRMT6 inhibitor." (PMID 35311114, 2022).
lung carcinoma (15 papers, 2012 to 2025). "In hepatocellular carcinoma, there is a significant correlation between decreased PRMT6 expression and short overall survival, whereas PRMT6 overexpression is associated with tumorigenicity and invasiveness in gastric cancer and lung cancer." (PMID 36792756, 2023). "In lung cancer PRMT6 activates tumor associated macrophages via interaction with ILF2." (PMID 40869229, 2025). "Once validated, this automated scoring system could be used in larger cohorts to assess the association of PRMT6 expression in lung cancer with socioeconomic and clinicopathologic characteristics." (PMID 37760550, 2023). "Moreover, given its connection to stress hormonal pathways, PRMT6 is an attractive candidate for studying the biological mechanisms underlying racial/ethnic disparities in lung cancer development and prognosis." (PMID 37760550, 2023). "Overexpression of PRMT6 is observed in various cancers, such as prostate, cervical, bladder, and lung cancers, making it a potential target for therapeutic intervention." (PMID 40869229, 2025). "Taken together, our results suggest that the increased expression of ILF2 by the PRMT1/PRMT6 heteromer promotes cell proliferation and likely contributes to lung cancer health disparities in Black/AA men." (PMID 38303720, 2024). "In summary, our study identified a unique role of the PRMT1/PRMT6 heteromer in driving lung cancer development which likely contributes to cancer health disparities in Black/AA men." (PMID 38303720, 2024). "In this study, we investigated the underlying mechanism of PRMT6 and its cooperation with PRMT1 to form a heteromer as a driver of lung cancer." (PMID 38303720, 2024). "Most importantly, our study shows that PRMT6 displays higher expression in lung cancer tissues of Black/AA men compared to NHW men." (PMID 38303720, 2024). "In other tumors, downregulating PRMT6 has been shown to decrease the aggressive characteristics of endometrial, prostate, and lung cancer cells, leading to a significant reduction in their ability to migrate and invade surrounding tissues." (PMID 39043634, 2024). "To demonstrate the proof of principle for the targeting of the PRMT1/PRMT6 heteromer in lung cancer, we showed that disrupting the complex reduced cell viability in LC PDOs from a Caucasian male (PDXO) and a Black/AA female (PDO)." (PMID 38303720, 2024). "We demonstrated that PRMT1/PRMT6 heteromer played a critical role in cell proliferation and perhaps lung cancer development." (PMID 38303720, 2024). "The findings of this study demonstrated that training algorithms for AI-based scoring can successfully replicate the level of accuracy of pathologists’ manual scoring of PRMT6 expression in lung cancer tissues." (PMID 37760550, 2023). "We trained and validated the machine learning digital scoring method of PRMT6 protein expression in lung cancer tissue samples." (PMID 37760550, 2023). "Accordingly, this study showed an alternative approach to PRMT6 scoring in lung cancer surgical specimens, which is automated and reliable." (PMID 37760550, 2023). "In conclusion, we successfully optimized a machine learning algorithm for scoring PRMT6 expression in lung cancer that matches the degree of accuracy of scoring by pathologists." (PMID 37760550, 2023). "When we dichotomized nuclear H-scores at the sample mean, 45.5% of lung cancer cases had high PRMT6 nuclear staining." (PMID 37760550, 2023). "Using HALO software, we optimized the digital method for scoring PRMT6 expression on immunohistochemically stained lung cancer tissue." (PMID 37760550, 2023). "PRMT6 expression in immunohistochemically labeled lung cancer tissues was evaluated by two independent pathologists blinded to the demographic and clinical characteristics of corresponding patients." (PMID 37760550, 2023). "PRMT6 was found to be expressed predominantly in the nuclei of cancer cells, agreeing with previously reported localization in lung cancer." (PMID 37760550, 2023).
lung carcinoma (continued). "Among these markers, PRMT6 was shown to be related to lung cancer and differentially expressed among racial/ethnic groups." (PMID 37760550, 2023). "PRMT6 is a crucial biomarker for the progression of lung cancer, and recently developed small molecule and peptide inhibitors of PRMTs highlight the therapeutic significance of studying PRMTs, especially in high-mortality diseases such as lung cancer." (PMID 37760550, 2023). "For example, PRMT6 knockdown can significantly inhibit the growth of bladder cancer and lung cancer cells." (PMID 35311114, 2022). "It was confirmed that PRMT6 is upregulated in lung cancer and can promote the growth of tumor cells." (PMID 35311114, 2022). "Several articles reported that PRMT6 aberrantly increased in many cancers like breast, prostate, gastric and lung cancer." (PMID 33260152, 2020). "PRMT6 protein is aberrantly overexpressed in several cancers including breast, prostate, and lung cancer, and its high level predicts better prognosis." (PMID 33260152, 2020). "siRNA-mediated knockdown of PRMT1 and PRMT6 was found to lead to suppression of lung cancer cell growth, most probably by influencing G1-S transition in the cell cycle." (PMID 23202904, 2012). "PRMT6 knockdown reduced the proliferation of bladder and lung cancer cell lines, as a result of a block in cell cycle progression." (PMID 22916108, 2012). "Thus, the next step is to utilize genetically engineered mouse models to demonstrate the role of PRMT1/PRMT6 heteromer in lung cancer." (PMID 38303720, 2024). "Higher PRMT6 levels in LUAD of Black/AA men may contribute to lung cancer health disparities observed in this particular cohort." (PMID 38303720, 2024). "Furthermore, in vivo mechanistic studies indicated that the lung-specific overexpression of PRMT6 in a murine model resulted in the spontaneous development of lung cancer and potentiated chemical carcinogen-induced lung cancer progression." (PMID 37760550, 2023). "Additionally, high levels of PRMT6 were represented in multiple cancer samples including thyroid, esophagus, stomach, colon, rectum, pancreas, and lung cancers, compared with paired normal tissues." (PMID 36941223, 2023). "Taking together, PRMT5 and PRMT6 may regulate tumor progression through different mechanisms in ovarian cancer and lung cancer, respectively." (PMID 36999124, 2023). "PRMT6 is an important biomarker for the progression of lung cancer; however, conventional pathologists’ manual scoring of its expression in large samples is time consuming, particularly when analyzing large sections of lung cancer tissue." (PMID 37760550, 2023). "The purpose of this study is to validate automated PRMT6 scoring in lung cancer surgical specimens." (PMID 37760550, 2023). "Targeting the newly identified PRMT6/ILF2/MIF axis may open new possibilities for lung cancer intervention." (PMID 35311114, 2022). "PRMT6 overexpression has been reported recently in several types of cancers, including melanoma 24 and bladder and lung cancers 25, suggesting that inhibition of PRMT6 might be a promising new strategy for therapeutic intervention." (PMID 31903111, 2020). "Similarly to previously published studies on breast, colon and bladder cancers, elevated PRMT1 and PRMT6 expression has recently been found in various types of lung cancer including SCLC and NSCLC." (PMID 23202904, 2012). "Disrupting PRMT1/PRMT6 heteromer by a competitive peptide reduced proliferation in non-small cell lung cancer cell lines and patient-derived organoids, therefore, giving rise to a more strategic approach in the treatment of Black/AA men with lung cancer and to eliminate cancer health disparities." (PMID 38303720, 2024). "Notably, dysregulation of PRMT6 expression, which has been consistently found in numerous studies, correlates with the aggressiveness of various human cancers such as prostate cancer, lung cancer, and gastric cancer." (PMID 39043634, 2024).
lung carcinoma (continued). "Together, our results implicate that high PRMT6 expression cooperates with PRMT1 to drive higher incidence and mortality rates of lung cancer in Black/AA men." (PMID 38303720, 2024). "We demonstrated that PRMT1 and PRMT6 formed a heteromer, and breaking this heteromer with a peptide inhibitor reduced cell proliferation and viability in NSCLC cell lines and lung cancer organoids." (PMID 38303720, 2024). "Thus, it is of interest to determine the role of ILF2 in lung cancer development and in mediating the function of the PRMT1/PRMT6 heteromer in vivo." (PMID 38303720, 2024). "In contrast, our data indicate that the other two type I PRMT proteins, PRMT4 and PRMT6, are counter-targets for persistent cancer cells: their knockdowns and/or pharmacological inhibitions promoted persistence across multiple EGFRmut and KRASG12C lung cancer cell lines." (PMID 39699269, 2025). "However, the in vivo role of ILF2 in driving lung cancer and whether the function of PRMT1/PRMT6 heteromer is mediated via ILF2 still await further investigation." (PMID 38303720, 2024). "Interestingly, in our previous report, we demonstrated that PRMT6 asymmetrically dimethylates the R9 and R372 sites of ENO1 in lung cancer, which is different from our finding in this study that PRMT5 only symmetrically dimethylates the R9 site of ENO1 in ovarian cancer." (PMID 36999124, 2023). "In addition, it has been reported that PRMT3 and PRMT6 are mainly overexpressed in breast, bladder and lung cancer but not CRC." (PMID 26078354, 2015). "Additionally, protein arginine methyltransferase 6 (PRMT6) mediated methylation at R9 and R372 of ENO1 promotes the formation of its active form and facilitates the binding of 2-phospho-glycerate to ENO1, thereby upregulating glycolysis and DDP resistance in lung cancer." (PMID 40264038, 2025).
glioblastoma (11 papers, 2021 to 2025). The most malignant astrocytic tumor (WHO grade IV). "Here, we aim to uncover the essential role and underlying mechanisms of PRMT6 in promoting glioblastoma (GBM) proliferation." (PMID 36792756, 2023). "Furthermore, transcriptional expression profile analysis showed that reducing PRMT6 levels in glioblastoma cells resulted in lower expression of molecules associated with tumor invasion." (PMID 39043634, 2024). "However, the effects of PRMT6 on glioblastoma cell invasion and migration and its underlying mechanisms remain elusive." (PMID 39043634, 2024). "In summary, high expression of PRMT6 is associated with poor prognosis and may promote the progression of glioblastoma." (PMID 38637831, 2024). "However, it remains to be determined whether PRMT6 is involved in the invasion process of glioblastoma and the underlying mechanism." (PMID 39043634, 2024). "In glioblastoma, PRMT6 methylates RCC1 at R214, enhancing its chromatin binding, promoting mitosis, stem cell expansion, and drug resistance." (PMID 41204384, 2025). "In dual-luciferase reporter gene assays, we found an increase in luciferase activity following the overexpression of PRMT6 in LN229 glioblastoma cell lines." (PMID 38637831, 2024). "Collectively, these findings indicate that elevated PRMT6 expression can the invasion and migration of glioblastoma cells." (PMID 39043634, 2024). "Existing studies have shown that PRMT6 is upregulated in gliomas and regulates the mitosis and tumorigenicity of glioblastoma stem cells by methylating RCC1, or promotes the proliferation of glioma cells by transcriptionally activating CDC20." (PMID 38637831, 2024). "These rescue experimental results indicate that EZH2 can restore the invasion and migration abilities of glioblastoma cells deprived of PRMT6, that is, PRMT6 induces glioblastoma cell invasion and migration via EZH2." (PMID 39043634, 2024). "Protein arginine methyltransferase 6 (PRMT6), as an epigenetic regulator, has been confirmed to promote the malignant proliferation of glioblastoma cells in previous studies." (PMID 39043634, 2024). "Inhibition of PRMT6 (using PRMT6 shRNA or inhibitor EPZ020411) reduces glioblastoma cell invasion and migration in vitro, whereas overexpression of PRMT6 produces opposite effects." (PMID 39043634, 2024). "Subsequent Co-IP experiments in glioblastoma cell lines confirmed the interaction between PRMT6 and CDK9." (PMID 38637831, 2024). "This suggests that PRMT6 promotes glioblastoma’s malignant traits via YTHDF2-mediated activation of the Wnt-β-catenin pathway." (PMID 38637831, 2024). "These experimental results confirm that PRMT6 and YTHDF2 promote the EMT and invasive phenotype of glioblastoma in vivo, and PRMT6 promotes tumor malignancy in vivo by regulating the expression of YTHDF2." (PMID 38637831, 2024). "Wound healing assays also showed that re-expression of EZH2 rescued the inhibition of glioblastoma cell migration ability by PRMT6 silencing." (PMID 39043634, 2024). "In this study, we present findings that highlight the significant role of PRMT6 in the invasion of glioblastoma cells both in vitro and in vivo." (PMID 39043634, 2024). "To explore the effect of PRMT6 on the malignancy of glioblastoma, we utilized lentiviruses carrying PRMT6 shRNA and overexpression plasmids to create cell lines with either decreased or increased PRMT6 expression." (PMID 38637831, 2024). "To understand how PRMT6 facilitates glioblastoma migration, invasion, and EMT through YTHDF2, we used TCGA and CGGA databases for GSEA pathway analysis." (PMID 38637831, 2024). "The results showed that depletion of PRMT6 increased both the mRNA and protein levels of TRAF6, while overexpression of PRMT6 suppressed the transcription of TRAF6 in glioblastoma cells." (PMID 39043634, 2024).